ELF5 (E74 like ETS transcription factor 5)
Description:
Transcriptionally activator that may play a role in regulating the later stages of keratinocytes terminal differentiation. Isoform 2 binds to DNA sequences containing the consensus nucleotide core sequence GGA[AT]. Transcriptionally activates SPRR2A and the parotid gland-specific PSP promoters.
Synonyms: ESE2
Tractability: No criterion of Open Targets' tractability assessment is met for any kind of drug.
Gene: Protein-coding gene on chromosome 11 (34,478,791 to 34,525,193, reverse strand). Ensembl gene ENSG00000135374.
Subcellular location: Nucleus
Subcellular location (Human Protein Atlas): Nucleoplasm
Pathways (Reactome):
Developmental Biology: Developmental Lineage of Mammary Gland Alveolar Cells; Developmental Lineage of Mammary Gland Luminal Epithelial Cells
Gene Ontology:
Molecular function: protein binding; sequence-specific double-stranded DNA binding; DNA-binding transcription factor activity, RNA polymerase II-specific; DNA-binding transcription activator activity, RNA polymerase II-specific; DNA-binding transcription factor activity; RNA polymerase II transcription regulatory region sequence-specific DNA binding; sequence-specific DNA binding
Biological process: cell differentiation; regulation of transcription by RNA polymerase II; positive regulation of transcription by RNA polymerase II; regulation of DNA-templated transcription
Cellular component: chromatin; nucleus; cytoplasm
Genetic constraint (gnomAD): Loss-of-function variants: 31 observed, 39.31 expected, observed/expected ratio (o/e) 0.79, 90% interval 0.59 to 1.06. The upper end of that interval is the gene's LOEUF score, 1.06, which puts it in group 4 of 6, group 1 being the genes least tolerant of losing a copy. Missense variants: 300 observed, 323.82 expected, observed/expected ratio (o/e) 0.93, 90% interval 0.84 to 1.02. Synonymous variants: 121 observed, 118.46 expected, observed/expected ratio (o/e) 1.02, 90% interval 0.88 to 1.19.
Homologues: Orthologues: chimpanzee ELF5 (99% identical), macaque ELF5 (99% identical), dog ELF5 (96% identical), pig ELF5 (95% identical), guinea pig ELF5 (95% identical), mouse Elf5 (95% identical), rat Elf5 (94% identical), rabbit ELF5 (92% identical), tropical clawed frog elf5 (59% identical). Paralogues in human: EHF (47% identical), ELF3 (34% identical), ETV6 (26% identical), GABPA (25% identical), FLI1 (25% identical), SPDEF (25% identical), ERG (24% identical), ETS1 (23% identical), ETS2 (22% identical), ETV7 (22% identical), ELF2 (22% identical), ETV4 (22% identical), and 16 more.
Diseases named in the same sentence as ELF5 in open-access papers:
ELF5 is named in the same sentence as 62 diseases in open-access papers, as found by Europe PMC text mining. Sharing a sentence is not in itself a finding about the gene and the disease. The quoted sentences say what the papers report.
breast cancer (51 papers, 2009 to 2025). A primary or metastatic malignant neoplasm involving the breast. "Emerging evidence from transcriptional profiling points to the downregulation of ELF5 as a pivotal driver of the aging phenotype in luminal epithelial progenitor cells, with potential implications for increased breast cancer susceptibility." (PMID 38275872, 2024). "Overall, understanding ELF5’s intricate role in breast biology and cancer susceptibility opens avenues for targeted interventions and personalized approaches in breast cancer prevention and early detection." (PMID 38275872, 2024). "We surmise that elevated ELF5, possibly due to loss of promoter demethylation, drives a limited lactation and involution in these breast cancers." (PMID 35505346, 2022). "We have previously shown that increased ELF5 can drive mammary cancer metastasis, establishing that ELF5 can cause the acquisition of the two defining features of progressive ER+ breast cancer, endocrine resistance and renewed metastasis." (PMID 31895944, 2020). "Forcing ELF5 expression causes ER+ breast cancer cells to adopt gene expression patterns more like those seen in the ER- subtypes." (PMID 31895944, 2020). "Preliminary studies have demonstrated that loss of Elf5 is frequently found in human mammary carcinoma cells and Elf5 mRNA expression also is lost in a number of breast cancers compared to adjacent normal tissues." (PMID 20831799, 2010). "The interplay between hormonal dynamics, particularly elevated progesterone levels in BRCA1 mutation carriers, the RANK/RANKL signaling pathway, and ELF5 may provide a crucial mechanistic link to the increased breast cancer risk observed in these individuals." (PMID 38275872, 2024). "ELF5 emerges as a potential breast-specific biomarker for age and risk, with its downregulation associated with an aging phenotype and heightened susceptibility to breast cancer." (PMID 38275872, 2024). "The unique age and risk-associated biology of ELF5 in the breast suggests it may have distinct uses in breast cancer prevention and early detection." (PMID 38275872, 2024). "Thus ELF5 is associated with the two key aspects of progression to the lethal phenotype in ER+ breast cancer, acquisition of endocrine resistance and renewed metastatic activity." (PMID 31895944, 2020). "Both tumour promoting and suppressive roles for ELF5 have been reported in breast cancer, which may be linked to the molecular subtype of the disease." (PMID 30200227, 2018). "However, sustained increased ELF5 expression in some contexts is associated with disease progression, such as in endocrine-resistant breast cancers, reliant on elevated ELF5 for growth in cell line models, and the basal-like subtype of breast cancer." (PMID 26738740, 2016). "Here, we show that the metastatic mechanism driven by ELF5 is most important in luminal breast cancer patients, in whom higher ELF5 expression is associated with low presence of cytotoxic T lymphocytes, an immune cell population responsible for tumor rejection." (PMID 26717410, 2015). "E74-like factor 5 (Elf5) has been associated with tumor suppression in breast cancer." (PMID 25629735, 2015). "The transcription factor ELF5 is responsible for gene expression patterning underlying molecular subtypes of breast cancer and may mediate acquired resistance to anti-estrogen therapy." (PMID 23300383, 2012). "Thus, we now see that ELF5 may be behind the two most important processes that cause luminal breast cancers to progress towards the lethal phenotype; resistance to antiestrogen therapy and the development of metastatic activity." (PMID 26717410, 2015). "ELF5 influences phenotypic plasticity by driving the expression of epithelial characteristics, as shown by the fact that knockout of Elf5 in mice, or knockdown of breast cancer cells, caused the loss of epithelial patterns of gene expression, while forced Elf5 expression caused their gain." (PMID 26717410, 2015).
breast cancer (continued). "Understanding the modulation of ELF5 expression within luminal epithelia and cKIT+ luminal progenitors is important for developing therapies targeted at age-related breast cancer prevention." (PMID 38275872, 2024). "In conclusion, a comprehensive understanding of ELF5 expression dynamics across the aging breast landscape is essential to inform targeted interventions for age-related breast cancer pathologies." (PMID 38275872, 2024). "ELF5, a member of the erythroblast transformation-specific (Ets) transcription factor family, has been extensively studied in breast cancer contexts." (PMID 39175753, 2024). "ELF5 expression in luminal epithelial progenitor cells implicates a complex interplay between cellular phenotype and breast cancer progression, with implications for tumor heterogeneity and treatment resistance." (PMID 38275872, 2024). "For example, ELF5 depletion can facilitate the metastasis of breast cancer by interferon-γ signaling." (PMID 37980532, 2023). "ELF5 is reported to be lowly expressed in luminal subtype breast cancer and its promoter methylation level is high." (PMID 37980532, 2023). "ChIP-seq analyses found that super-enhancers in estrogen receptor (ER)-positive breast cancer cells co-localize with ELF5, FOXA1, and ER." (PMID 36232979, 2022). "In summary, we report that PTHrP overexpression activates STAT5, increases Elf5 expression, and leads to increased proliferation and secretory differentiation of both normal mammary epithelial cells and mammary tumor cells in mice." (PMID 35440032, 2022). "INAVA expression is associated with regulating two transcription factors, ELF5 and GATA3, which are important in breast stem cells, and targeting INAVA has therapeutic value in breast cancer." (PMID 35719392, 2022). "Acetylation of ELF5 was found to enhance its ability to inhibit the progression of breast cancer via direct regulation of CCND1 expression." (PMID 33742100, 2021). "ELF5 expression is also upregulated in basal-like breast cancer and endocrine-resistant breast cancer." (PMID 33742100, 2021). "Immunohistochemical staining of 48 breast cancer tissue samples shed further light on the pathological relevance of ELF5 in the regulation of Cyclin D1 expression in breast cancer." (PMID 33742100, 2021). "The inhibitory effect of ELF5 in breast cancer was abolished when Cyclin D1 was overexpressed or CCND1 was knockdown." (PMID 33742100, 2021). "ELF5 was found to be downregulated in several types of cancer tissues, especially that of breast cancer." (PMID 33742100, 2021). "ELF5 was identified as an acetylated protein in breast cancer cells and later shown to be subject to regulation by the acetyltransferases p300 and the deacetylase SIRT6." (PMID 33742100, 2021). "Data obtained from CCK8 assay, colony formation, and xenograft mouse model indicated that acetylation of ELF5 is vital for its inhibition of cell proliferation in breast cancer." (PMID 33742100, 2021). "In luminal breast cancer, ELF5 inhibits the transcription of ER, FOXA1, EGFR, MYC, and other proliferation-related genes, resulting in the suppression of estrogen sensitivity." (PMID 33742100, 2021). "To further test the physiological function of ELF5 acetylation in breast cancer cells, we investigated the effect of ELF5 acetylation on cancer cell proliferation and tumor growth in mice." (PMID 33742100, 2021). "In this study, we demonstrated that ELF5 is one of the p300-interacting proteins in human breast cancer cells." (PMID 33742100, 2021). "A sustained increase in ELF5 expression has been demonstrated in endocrine-resistant breast cancers and basal-like subtype breast cancer." (PMID 33742100, 2021). "ELF5 levels increase when MCF-7 breast cancer cells are made resistant to endocrine therapies, and these cells also become dependent on ELF5 for their proliferation." (PMID 31895944, 2020). "ELF5 was established as a suppressor of epithelial-mesenchymal transition that inhibited metastasis in breast cancer." (PMID 33216733, 2020).
breast cancer (continued). "In luminal A breast cancer patients treated with tamoxifen, high ELF5 expression strongly predicted early treatment failure and disease progression." (PMID 31895944, 2020). "The set of genes showing differential expression in T-47D breast cancer cells in response to induction of ELF5 was very significantly (padj = 1.6E-5 GSEA) enriched, demonstrating that the effects seen in MCF-7 cells also occurred in another cell line." (PMID 31895944, 2020). "In mice, forcing ELF5 expression results in mammary tumor angiogenesis and an increase in lung metastasis via regulation of the innate immune system." (PMID 31895944, 2020). "We found that MYH11, TP63 and ELF5 were downregulated in breast cancer tissues, which is consistent with previous findings highlighting TP63 and ELF5 as tumor suppressors." (PMID 33216733, 2020). "ELF5 has also been suggested to regulate oestrogen sensitivity of breast cancers, as ELF5 repressed ER expression in MCF7 cells." (PMID 30200227, 2018). "Overexpression of the cell fate decision determinant Elf5 is a known driving force behind breast cancer progression and metastasis." (PMID 30194301, 2018). "Its expression is altered in multiple cancers; in breast cancer, elevated ELF5 suppresses oestrogen sensitivity and correlates with the ER− negative basal subtype." (PMID 28193698, 2017). "In luminal breast cancer, progesterone signalling induces Elf5 and activates a number of immune functions." (PMID 28193698, 2017). "ELF5 also plays key roles in malignancy, particularly in basal-like and endocrine-resistant forms of breast cancer." (PMID 26738740, 2016). "Extensive in vitro analysis of ELF5 isoforms, including a 116-gene quantitative polymerase chain reaction panel, was performed in breast cancer cell lines." (PMID 26738740, 2016). "In breast cancer, ELF5 alterations were subtype-specific, with the basal subtype demonstrating unique ELF5 isoform expression changes." (PMID 26738740, 2016). "This indicates that endogenous ELF5 can localize to the cytoplasm and that this has functional significance in breast cancer." (PMID 26738740, 2016). "Knockdown of ELF5 levels in luminal breast cancer cells has a small effect on proliferation, but a much greater effect is seen in ER- basal cell lines." (PMID 26717410, 2015). "In breast cancer, ELF5 is a key transcriptional determinant of tumor subtype and has been implicated in the development of insensitivity to anti-estrogen therapy." (PMID 26717410, 2015). "Our previous work demonstrated that in luminal breast cancer, ELF5 is a key determinant of antiestrogen therapy resistance." (PMID 26717410, 2015). "The transcription factor Elf5 defines hormone-insensitive and endocrine-therapy–resistant breast cancer." (PMID 26717410, 2015). "Time course experiments showed that after 7 d of Doxycycline (DOX) in the feed the ELF5 protein was detectable by western blot in established mammary tumors and that expression was maintained for at least 8 wk." (PMID 26717410, 2015). "ELF5 has been proposed by Chakrabati and colleagues as a metastasis suppressor gene for all breast cancers, but our studies demonstrate that the luminal A subgroup shows the opposite response." (PMID 26717410, 2015). "Taken together, these findings confirm our observations made in human breast cancer cells regarding the function of ELF5, and indicate that, in vivo, these effects are coupled with the immune system, both in the PyMT model and in luminal A human breast cancer." (PMID 26717410, 2015). "Our results in human breast cancer are consistent with our observations in mice suggesting the implication of ELF5 in a tumor permissive inflammatory environment." (PMID 26717410, 2015). "As ELF5 has been previously implicated in the development of antiestrogen resistance, this finding implicates ELF5 as a defining factor in the acquisition of the key aspects of the lethal phenotype in luminal A breast cancer." (PMID 26717410, 2015).
breast cancer (continued). "An interesting observation, given that ELF5 is a nuclear transcription factor, is that cytoplasmic rather than nuclear staining provides this prediction in luminal A breast cancer patients." (PMID 26717410, 2015). "We have used our inducible mouse model of mammary-specific ELF5 expression, in the context of luminal mammary tumors induced by PyMT expression, to investigate the roles played by ELF5 during mammary carcinogenesis and progression to metastatic disease." (PMID 26717410, 2015). "To investigate the effects of Elf5 expression in breast cancer progression, we crossed our mammary epithelial specific ELF5-inducible transgenic mouse with the MMTV-PyMT mouse model of luminal mammary cancer." (PMID 26717410, 2015). "For example, forced expression of Elf5 in ER-positive luminal breast cancer cells reduced ER and FOXA1 expression and suppressed the luminal subtype molecular signature." (PMID 25080108, 2014). "Elf5 is a transcription factor present in mammals that significantly inhibits breast cancer and certain hormone-related tumors." (PMID 24959289, 2014). "Knockdown of Elf5 in basal breast cancer cells also resulted in a shift in their molecular signature toward a claudin-low and normal-like subtype of breast cancer suggesting that Elf5 is a key determinant of breast cancer intrinsic molecular subtype." (PMID 25080108, 2014). "We examined the ability of the direct transcriptional targets of ELF5 to predict aspects of breast cancer phenotype." (PMID 23300383, 2012). "In this report we show that ELF5 exerts wide transcriptional effects with functional outcomes on cell proliferation, adhesion, the molecular determinants of breast cancer subtype and phenotype, and acquired resistance to Tamoxifen." (PMID 23300383, 2012). "To test this we constructed inducible models of ELF5 expression in ER positive luminal breast cancer cells and interrogated them using transcript profiling and chromatin immunoprecipitation of DNA followed by DNA sequencing (ChIP-Seq)." (PMID 23300383, 2012). "Here, we show that the transcription factor ELF5 is responsible for much of the patterning of gene expression that distinguishes the breast cancer subtypes." (PMID 23300383, 2012). "We propose that the effects of ELF5 in the breast cancer cell lines represent a carry over of the normal developmental role of ELF5 into breast cancer." (PMID 23300383, 2012). "Significantly for clinical management of breast cancer, elevation of ELF5 is a mechanism by which MCF7 cells can become insensitive to antiestrogen treatment." (PMID 23300383, 2012). "We knocked down ELF5 in two basal breast cancer cell lines and observed a significant and sustained reduction in cell accumulation rate, which was not seen in luminal cells." (PMID 23300383, 2012). "Knockdown of ELF5 in basal breast cancer cell lines suppressed basal patterns of gene expression and produced a shift in molecular subtype toward the claudin-low and normal-like groups." (PMID 23300383, 2012). "We chose to investigate Muc4 as a potential direct transcriptional target of Elf5 since Muc4 has a role in the pregnant mammary gland in rodents and in humans and dysregulated expression of MUC4 has been associated with breast cancer." (PMID 20949099, 2010). "In the T47D breast cancer cell line, exogenous addition of ELF5 was able to induce expression from the MUC4 promoter." (PMID 20949099, 2010). "Several candidate factors in our dataset have been correlated with disease states including the Ets family member Elf5, which is upregulated in breast cancer." (PMID 19156209, 2009). "In addition to these clearly malignant clusters, we identified a population of luminal progenitor-like cells (LP; KIT, ELF5), which are considered the presumptive cells of origin for breast cancer and are indicative of cancer stemness." (PMID 40858992, 2025).